IGFBP2 (insulin like growth factor binding protein 2)
Diseases named in the same sentence as IGFBP2 in open-access papers (continued):
Sharing a sentence is not in itself a finding about the gene and the disease.
prostate carcinoma (continued). "In summary, IGF-I and hyperglycaemia-induced FOXA1/IGFBP-2 play important roles in promoting prostate cancer cell progression." (PMID 32655839, 2020). "Elevated serum levels of IGFBP2 have also been discovered in patients with breast, ovarian and prostate cancer." (PMID 29630649, 2018). "Silencing IGFBP-2 expression reduces the resistance to docetaxel in prostate cancer cells and results in significant sensitization to cisplatin in esophageal adenocarcinoma cells." (PMID 28977895, 2017). "This was shown in prostate cancer cells where IGFBP-2 transcription was induced in high glucose due to acetylation of histones H3 and H4 associated with the Igfbp-2 promoter region." (PMID 29088813, 2017). "The appearance of IGFBP2 in our gene signature was reassuring, since decreased expression of this gene has been reported to be a predictor of prostate cancer recurrence after radical prostatectomy." (PMID 27966447, 2017). "Previously, we reported that in prostate cancer cells glucose increased resistance to chemotherapy through upregulating IGFBP-2." (PMID 29088813, 2017). "In primary human prostate stromal cells and in human prostate cancer cells (LNCaP), androgens and in part also E2 significantly induced IGFBP-2 mRNA expression." (PMID 24778626, 2014). "A reduction of IGFBP-2 proteolysis in androgen-insensitive prostate carcinoma cells increased the metastatic potential in that study." (PMID 24778626, 2014). "The IGFBP-2 is considered a key factor in prostate cancer progression with levels of IGFBP-2 being elevated in patients with CaP, both in serum where levels correlate with those of PSA and in the tumours." (PMID 21487405, 2011). "The IGFBP-2 has a key role in the growth of prostate cancer cells, and silencing IGFBP-2 expression reduced the resistance of these cells to docetaxel." (PMID 21487405, 2011). "The aim of this study is to investigate the effects of insulin-like growth factor-binding protein-2 (IGFBP-2) on prostate cancer cell proliferation and its effects on the response to docetaxel." (PMID 21487405, 2011). "Expression of IGFBP-2 has also been reported to increase following castration and to promote the growth of androgen-independent prostate cancer cells." (PMID 21487405, 2011). "Higher BMI is associated with lower concentrations of IGFBP-1 and IGFBP-2, which might lead to higher bioavailability of IGF-I, but evidence on the association of these binding proteins with prostate cancer mortality is very limited." (PMID 35509091, 2022). "We have reported that IGFBP-2 can promote prostate tumour progression by acting as a growth promoter, a survival factor against docetaxel-induced cell death and that hyperglycaemia-induced up-regulation of IGFBP-2 conferred chemo-resistance in prostate cancer cells." (PMID 32655839, 2020). "There is accumulating evidence that IGFBP-2 may have an important role in prostate cancer progression." (PMID 32655839, 2020). "Interestingly, nuclear localisation of IGFBP-2 was also observed in both adjacent benign and prostate cancer cases." (PMID 32655839, 2020). "Interestingly, in the smaller tissue cohort we found a positive correlation between FOXA1 and IGFBP-2 levels (r = 0.319, p = 0.029) in prostate cancer tissue." (PMID 32655839, 2020). "Previously, we examined levels of IGF axis analytes within the PCPT and reported an association of increased serum IGFBP-2 with prostate cancer risk in the placebo, but not the finasteride, arm of the study." (PMID 28417914, 2017). "IGFBP-2 proteins may have IGF-independent roles as well, and may be associated with prostate cancer progression." (PMID 28417914, 2017). "In the current study, IGFBP-2 did not modify the associations of serum 25(OH)D with prostate cancer in spite of the positive correlation between 25(OH)D and IGFBP-2 at baseline." (PMID 28417914, 2017). "No strong associations were observed for IGF-II, IGFBP-1 or IGFBP-2 with either milk intake or prostate cancer risk." (PMID 28361446, 2017).
prostate carcinoma (continued). "The role of IGFBP-2 as a potential biomarker for prostate cancer was evaluated in a large case control study; however, serum IGFBP-2 did not predict risk of prostate cancer." (PMID 26217584, 2015). "However, also prostate carcinoma cells are known to express NeuroD and, as discussed further down, also IGFBP-2." (PMID 24778626, 2014). "Similarly, IGFBP2 and 4 (insulin like growth factor binding proteins 2 and 4) are biomarkers for advanced prostate cancer stages." (PMID 22848758, 2012). "We have confirmed that IGFBP-2 promoted the growth of DU145 prostate cancer cells and also showed that IGFBP-2 could function as a mitogen for PC3 cells." (PMID 21487405, 2011). "Our data support previous findings, suggesting that IGFBP-2 may be a key factor in the progression of prostate cancer." (PMID 21487405, 2011). "In addition, IGFBP2 has been found to stimulate the growth of prostate cancer cells, an effect that can be blocked by MAP-kinase and PI3-kinase inhibitors." (PMID 15686601, 2005). "Thus, miR-34a-5p/HIF1A, miR-34a-5p/IGFBP2 and miR-34a-5p/PIK3CB, as well as Axl, could represent possible biomarkers and therapeutic targets for prostate cancer; conversely, miR-34a-5p upregulation is associated with the development of AD." (PMID 35741059, 2022). "When metformin was used to treat prostate cancer cells, the resistance of prostate cancer cells to docetaxel was inhibited under hyperglycemic conditions, indicating that metformin can restore the sensitivity of prostate cancer cells to docetaxel through decreasing IGFBP-2 levels." (PMID 31337431, 2019). "Additionally, it has been demonstrated that the expression levels of PTEN and IGFBP2 are inversely correlated in human brain and prostate cancers, and it was suggested that IGFBP2 is a potential serum biomarker of PTEN status and PI3K/AKT pathway activation in patients with cancer." (PMID 30231881, 2018). "Two potential androgen binding sites have been identified via bioinformatic analysis of the region upstream from the IGFBP-2 transcription initiation site that may explain the effects of androgen treatment on IGFBP-2 gene expression as demonstrated in prostate cancer cells." (PMID 24778626, 2014). "In addition, there is accumulating evidence that IGFBP-2 may have an important role in prostate cancer progression." (PMID 21487405, 2011). "We have shown previously that IGFBP-2 promotes prostate cancer growth in both an IGF-I-dependent and independent manner and that hyperglycaemia induced up-regulation of IGFBP-2 in prostate cancer cells which resulted in resistance to chemotherapy." (PMID 32655839, 2020). "Moreover, overexpression of IGFBP2 has been associated with resistance to docetaxel or paclitaxel and anti-hormone therapy in prostate cancer, suggesting that IGFBP2 induced functional changes in cancer cells could play a critical role in the efficacy of anticancer therapy." (PMID 29500455, 2018). "Here we show that a four-gene signature based on HBEGF, HOXC13, IGFBP2, and SATB1 was able to identify patients whose prostate cancer recurred." (PMID 27966447, 2017). "In silico analysis to map the function of these secreted factors identified PAPPA, IGFBP2, DKK1, and TGFβ1, which have documented effects on “invasion of tumor cells” or “prostate cancer and tumors”." (PMID 29088840, 2017). "Indeed, inconsistent with the strong downregulation of Igfbp2 mRNA that we observed in the liver of LPTENKO mice, PTEN was shown to inhibit IGFBP2 expression, while PI3K/AKT activation increases its expression in human brain and prostate cancer." (PMID 35409319, 2022). "This confirmed that IGFBP-2 could function either in an intrinsic, IGF-independent manner or in an IGF-dependent manner to promote prostate cancer cell proliferation." (PMID 21487405, 2011).
prostate carcinoma (continued). "However, stress-induced increase in several antiapoptotic genes, such as bcl-2, clusterin, insulin-like growth factor binding protein-2 (IGFBP-2), IGFBP-5 and heat-shock protein 27, have been shown to have important functions in the AI progression of prostate cancer after castration." (PMID 19844233, 2009). "We show that systemic dysregulation of CRGs is also found in prostate cancer, including a 4-gene signature (HBEGF, HOXC13, IGFBP2, and SATB1) capable of differentiating recurrent from non-recurrent prostate cancer." (PMID 27966447, 2017). "In ∼700 men without prostate cancer and two replication cohorts (N ∼ 900 and ∼9,000), we examined the properties of these SNPS as instrumental variables (IVs) for IGF‐I, IGF‐II, IGFBP‐2 and IGFBP‐3." (PMID 27225428, 2016).
diabetes (48 papers, 1998 to 2026). "An observational study exploring the relationship between protein, specifically IGFBP2, and diabetes suggested an inverse association." (PMID 38375323, 2024). "We also performed NOD-specific super enhancer analysis using H3K27ac ChIP-Seq signals in NOD ES cells and found a subset of top super enhancers, Pcmtd1, CD16 and Igfbp2, which were previously implicated in diabetes genome-wide association studies (GWAS)." (PMID 32796510, 2020). "When we examined the super enhancers in NOD ES cells, we found that Pcmtd1, Fcgr3 and Igfbp2 are implicated in human diabetes from GWAS studies." (PMID 32796510, 2020). "It seems likely that IGFBP1 and IGFBP2 have a beneficial effect on the risk of developing diabetes." (PMID 34371941, 2021). "Univariate and multivariate survival analyses results suggest that plasma IGFBP2 level is an independent prognostic factor when adjusted for diabetes status, lymph nodes involvement, and distant metastasis." (PMID 39221034, 2024). "As far as we know, our study is the first to compare the level of IGFBP2 in PDAC patients stratified by their diabetes status." (PMID 39221034, 2024). "The data suggests that IGFBP2 has the potential to distinguish between the two types of diabetes in PDAC." (PMID 39221034, 2024). "Higher plasma IGFBP2 is correlated with the new onset diabetes, lymph node involvement, distant metastasis, and advanced stage." (PMID 39221034, 2024). "The overexpression of IGFBP2 by an adenovirus reversed diabetes in insulin-resistant ob/ob and diet-induced obese mice." (PMID 37509659, 2023). "Yet, adenoviral overexpression of IGFBP2 has been shown to improve steatosis and diabetes in obese mice." (PMID 33324350, 2020). "These include IGFBP-2 and AGER associated with diabetes complications, and MMP-3 associated with extracellular remodeling." (PMID 33053810, 2020). "Our study confirmed previously established associations with incident diabetes for CD163, FABP4, PAI, and IGFBP-2." (PMID 30670722, 2019). "Over expression of IGFBP-2 by an adenovirus leading to very high concentrations of IGFBP-2 reversed diabetes in insulin-resistant ob/ob mice, diet-induced obese mice, as well as insulin-deficient streptozotocin-treated mice." (PMID 30392760, 2019). "An interesting aspect is that IGFBP2 has also been involved in diabetes and cancer." (PMID 34073526, 2021). "When further adjusting for established risk factors (model 2), all 7 proteins remained significantly associated with incident diabetes; 5 proteins (CD163, Gal-4, CTSD, PAI and FABP4) with an increased risk of diabetes and 2 proteins (PON3 and IGFBP-2) with a decreased risk for incident diabetes:." (PMID 30670722, 2019). "In addition, diabetes impairs hippocampal function through glucocorticoid, whereas stress (e.g., hypoxia) enhances IGFBP-2 levels in the hippocampus." (PMID 31824433, 2019). "Longitudinal measurements of renal and systemic concentrations of IGF2 and IGFBP2 in diabetes and diabetic nephropathy will be needed to clarify which of these potential mechanisms results in the independent relation between higher circulating IGFBP2 and more adverse renal outcome over time." (PMID 23781310, 2012). "Finally, overexpression of Igfbp2 reverses diabetes and steatosis in obese mice." (PMID 31389294, 2020). "Moreover, the leptin-induced overexpression of IGFBP-2 has been shown to reverse diabetes in insulin-resistant obese mice and hyperinsulinemic clamp studies showed a threefold improvement in hepatic insulin sensitivity following IGFBP-2 treatment of ob/ob mice." (PMID 29422987, 2017). "Taken together, these findings indicate that IGFBP-2 might be a new target of metformin action in diabetes and the metformin-AMPK-Sirt1-PPARα-IGFBP-2 network may provide a novel pathway that could be applied to ameliorate metabolic syndromes by controlling IGF-1 bioavailability." (PMID 27009398, 2016).
diabetes (continued). "For instance, IGFBP2, NPAS2, NDUFS7, and TGM2 showed differential expression in α cells from individuals with T2D and have previously been shown to affect diabetes and islet-related phenotypes or mitochondrial function." (PMID 36656641, 2023). "Therefore, the relevance of IGFBP-2 to metabolic disorder could be a main driver in the investigation of IGFBP-2’s underlying physiological function and may be an important candidate to protect against insulin resistance to diabetes, in obese individuals." (PMID 31547433, 2019). "The effect of diabetes on mRNA expression at each time point varied among IGF1R, IGFBP1, IGFBP2, and IGFBP3." (PMID 23878504, 2013). "In our cohort, PDAC patients with a long history of diabetes exhibited lower plasma IGFBP2 levels than those without diabetes history." (PMID 39221034, 2024). "This elevation in IGFBP2 with TRE, potentially impacting the AKT/mTOR pathway, may have implications for cardiovascular disease, diabetes, cancer, and aging." (PMID 39458471, 2024). "In our study, we demonstrated that hypermethylation of the specific murine Igfbp2 promoter region is not simply dependent on diabetes state, as the alb-SREBP-1c mice already display specific hepatic insulin resistance but no changes in IGFBP2 secretion." (PMID 32532003, 2020). "A negative correlation of IGFBP2 with body composition, BMI, metabolic syndrome, type 2 diabetes mellitus, or NAFLD, and a positive correlation to insulin sensitivity independent to BMI were described." (PMID 32532003, 2020). "Diabetes increased the expression of IGFBP2 after 12 weeks and IGFBP3 after 4 and 12 weeks, but did not change the expression of IGF1R or IGFBP1." (PMID 23878504, 2013). "Interestingly, we observed a remarkable aberrantly higher level of IGFBP2 in PDAC patients with new-onset diabetes than in PDAC patients with long-term diabetes or no diabetes." (PMID 39221034, 2024). "In our analysis, the expression of IGFBP2 differed between patients with and without diabetes." (PMID 39221034, 2024). "Patients with long-term diabetes had a relatively lower IGFBP2 than those without diabetes (336.4 ± 205.3 ng/mL vs 442.6 ± 176.2, P = 0.0359), while patients with new-onset diabetes exhibited a significantly higher IGFBP2 (585.4 ± 317.2 ng/mL) than patients without diabetes (P = 0.0466)." (PMID 39221034, 2024). "Furthermore, serum IGFBP-2 was higher in nonusers of HT at baseline and among those without a history of diabetes." (PMID 26106415, 2015). "However, other studies in STZ-diabetes rats have not demonstrated increased renal IGFBP2 mRNA levels in this model of diabetic nephropathy." (PMID 23781310, 2012). "However, one shortcoming of our study is the lack of diabetes status for the healthy controls; with that information, we could have determined the potential of IGFBP2 as an effective biomarker for PDAC screening in the diabetes risk group." (PMID 39221034, 2024). "Diabetes induced an increase in immunoreactive ANGPT2 (p < 0.05) but did not alter ANGPT1, VEGFA, VEGFB, IGFBP2 or SEMA6A." (PMID 31001672, 2019).
melanoma (42 papers, 2013 to 2025). A malignant, usually aggressive tumor composed of atypical, neoplastic melanocytes. "Tumor-specific expression of IGFBP2 in melanoma is associated with an ICI-favorable immune environment, showing this method can successfully uncover meaningful biological signals for cell type-specific expression patterns." (PMID 37433281, 2023). "Supporting these findings, the authors showed that IGFBP2 transcript and protein levels were associated with poor prognoses for primary melanoma patients." (PMID 36497341, 2022). "Strikingly, we observed that IGFBP2 protein levels correlated with resistance to MAPKi in several BRAF-mutant melanoma cell lines and are associated with poor prognosis in primary melanomas." (PMID 32042336, 2020). "By probing The Cancer Genome Atlas (TCGA), we found significant upregulation of IGFBP2 mRNA and protein in melanoma harboring BRAF mutation compared to other mutational subtypes." (PMID 30143629, 2018). "In models of melanoma, it was found that HIF-1α activation downstream of melanoma differentiation-associated gene 9 induced expression of IGFBP-2, which promoted endothelial cell migration into the tumor, increasing VEGF-A expression and angiogenesis, enhancing tumor survival." (PMID 41226289, 2025). "Loss of PTEN in melanoma may therefore increase levels of IGFBP2 and, we hypothesize, impact the standard of care (BRAF/MEK inhibition) for melanoma cells." (PMID 39007351, 2024). "We performed qRT-PCR on melanoma cells cultured with young and aged CM to determine whether treatment with CM caused an increase in transcription of IGFBP2 in melanoma cells." (PMID 39007351, 2024). "Finally, we found that IGFBP2 protein and mRNA levels are associated with poor prognosis in primary melanoma, supporting IGFBP2 as a potential biomarker for MAPKi resistance in melanoma." (PMID 30143629, 2018). "Further studies on melanoma identified IGFBP2 as a direct downstream target of MDA-9/Syntenin, which regulates endothelial cell proliferation, migration, and invasion." (PMID 40728947, 2025). "Fibroblast secretion of IGFBP-2 in aged models has been found to be a potent promoter of melanoma metastasis in vivo and cell migration in vitro." (PMID 41226289, 2025). "Our results suggest that aged dermal fibroblasts increase melanoma cell aggressiveness through increased secretion of IGFBP2, stressing the importance of considering age when designing studies and treatment." (PMID 39007351, 2024). "To confirm that this increase in p-AKT was mediated by IGFBP2, we cultured human melanoma cells with young CM and young CM with recombinant IGFBP2 (rIGFBP2)." (PMID 39007351, 2024). "Our data show that aged fibroblasts secrete elevated levels of IGFBP2, which elevates the metastatic capacity of melanoma cells." (PMID 39007351, 2024). "Conversely, ectopically treating melanoma cells with recombinant IGFBP2 in the presence of conditioned media from young fibroblasts or overexpressing IGFBP2 in melanoma cells promoted lipid synthesis and accumulation in melanoma cells." (PMID 39007351, 2024). "In the current study, we explore the expression of IGFBP2 in melanoma cells in an aged versus young microenvironment and its subsequent impact." (PMID 39007351, 2024). "IGFBP2 functionally triggers upregulation of the PI3K-dependent fatty acid biosynthesis program in melanoma cells." (PMID 39007351, 2024). "When built into reconstructs with aged fibroblasts, melanoma cells increased the expression of IGFBP2." (PMID 39007351, 2024). "We found that knockdown of IGFBP2 in the aged fibroblasts decreased BODIPY staining in melanoma cells." (PMID 39007351, 2024). "As we observed an increase in signaling through the Akt and Mtor pathways in the RPPA data, we wanted to confirm that increased Igfbp2 altered these signaling pathways in melanoma." (PMID 39007351, 2024).